EGFR (epidermal growth factor receptor)
Diseases named in the same sentence as EGFR in open-access papers (continued):
Sharing a sentence is not in itself a finding about the gene and the disease.
lung cancer (continued). "EGFR mutations were mainly trunked, which means that EGFR driver mutations may be defined as early events involved in the early tumorigenesis of multiple primary lung cancers before clonal expansion." (PMID 34804960, 2021). "Furthermore, ABL1 can promote metastasis of lung cancer cells carrying also EGFR or KRAS mutations." (PMID 33596996, 2021). "In this case, an NSCLC patient was diagnosed with secondary MDS via NGS analysis, indicating that the NGS analysis may serve as supplementary for diagnosis of secondary MDS and provide useful information of therapeutic regimens for subsequent-line treatment of EGFR-mutated lung cancer." (PMID 34930266, 2021). "However, lung cancer still ranks the first among causes of cancer-related death in the United States, and the emergence of primary or acquired resistance severely hampers the response to EGFR-TKIs in almost every patient." (PMID 33467099, 2021). "Furthermore, whether EGFR/ERK1/ERK2 or WNT1/WNT5A/WNT7B gene expression was potentially associated with the OS of lung cancer patients was assessed by Kaplan-Meier curve and Log-rank test." (PMID 34122668, 2021). "However, the biological process between lncRNAs and drug resistance to EGFR-mutated lung cancer remains largely unknown." (PMID 33924522, 2021). "In addition, KRT19 mRNA was increased about 2-fold in wild type (wt) lung cancer compared with EGFR mutated lung cancer, suggesting that EGFR pathway might affect KRT19 gene expression." (PMID 33442422, 2021). "In summary, a high discordance of EGFR mutations were identified between tumors in patients with SMPLA, so the detection of EGFR mutation may be used routinely to prevents unnecessary adjuvant treatment for patients with histologically similar synchronous primary lung cancers." (PMID 35096585, 2021). "To demonstrate this hypothesis, in the present study, we compared the therapeutic efficacy between chemotherapy and first‐ or second‐generation EGFR TKIs as the second‐line treatment in EGFR‐mutated non‐small cell lung cancer (NSCLC) patients with T790M‐negative or unknown mutation." (PMID 33586356, 2021). "Interestingly, resistance mechanisms to oncological drugs based on drug‐efflux, cell apoptosis, autophagy, and cancer cell stemness, as well as, mutations in TK receptors (e.g. EGFR) have partially been explained for both chemotherapy and targeted therapy in lung cancer." (PMID 33433063, 2021). "This study was also the first to report the incidence of EGFR mutation-specific lung cancer in Māori and Pacifica, the populations of interest in New Zealand, revealing that these populations had increased risk of developing EGFR mutation-positive lung cancer, as seen for lung cancer overall." (PMID 33961689, 2021). "Notably, activating mutations of EGFR in human lung carcinoma are a favorable predictor of response to tyrosine kinase inhibitors, and the standard first line therapy may be altered with specific mutations." (PMID 34403435, 2021). "The specific prognosis of EGFR-mutated lung cancer with choroidal metastases is unknown." (PMID 33272243, 2020). "Interestingly, the combination is undergoing clinical evaluation in a phase II trial (ClinicalTrials.gov NCT04545710), started in September 2020, that has been evaluating abemaciclib combined with osimertinib in resistant EGFR mutated lung cancer patients post progression on osimertinib." (PMID 33374971, 2020). "Non‐small cell lung cancer EGFR mutation could promote CD8 T cell apoptosis more than wild‐type." (PMID 32500560, 2020). "Hence, defining EGFR mutation status is a critical step in lung cancer diagnosis." (PMID 32292420, 2020).
lung cancer (continued). "Therefore, measuring exoRNA and ctDNA in BWF specimens may greatly improve the detection of EGFR mutations, even at an early stage of lung cancer; however, further studies are needed to evaluate this possibility." (PMID 32517757, 2020). "Therefore, PAK1 overexpression could serve as a molecular target for the treatment of EGFR mutation-positive lung cancer, especially among male patients and current/former smokers." (PMID 33261184, 2020). "However, the effect of glucocorticoids on the efficacy of EGFR-TKIs in patients with advanced lung cancer and EGFR-activating mutations remains unclear." (PMID 32917914, 2020). "However, HER2 dimerization is important in lung cancer, including EGFR mutated NSCLC." (PMID 32922539, 2020). "Our results demonstrating that EREG in HNSCC can mimic EGFR mutations by sustaining activation of the EGFR-Erk pathway raised the question of whether EREG could be used to identify the patient group most responsive to EGFR-targeted therapies, similar to EGFR-activating mutations in lung cancer." (PMID 32929368, 2020). "Thus, a combined model of clinico-pathologic features and radiomic model may enhance diagnostic performance for predicting EGFR mutation status in lung cancer BMs from larger populations which is expected to be validated in future study." (PMID 32483122, 2020). "An epidermal growth factor receptor (EGFR) exon 21 p.L858R missense mutation was identified which, to the best of our knowledge, is the first case to be reported of a common gene mutation associated with non‐small cell lung cancer (NSCLC) being found in a BA lesion." (PMID 33063939, 2020). "Moreover, transient inhibition of IGF-1R with osimertinib could lead to the eradication of EGFR-mutated lung cancer cells." (PMID 32929081, 2020). "The aim of our study was to investigate whether metformin could inhibit NF-κB signaling in EGFR-mutant lung cancer, and if so, whether it could have anticancer effects on lung cancer and anti-resistance efficacy against acquired EGFR TKIs resistance and underlying mechanisms." (PMID 33014814, 2020). "The successful applying of epidermal growth factor receptor (EGFR) tyrosine kinase inhibitor (TKI) in non-small cell lung cancer (NSCLC) patients who harbored EGFR mutations has dramatically changed the therapeutic approach of lung cancer and led to a more individualized treatment era." (PMID 32411601, 2020). "Traditional treatment for lung cancer has been surgery and radiochemotherapy, but targeted therapies are increasingly adopted for patients who have the druggable aberrations such as epidermal growth factor receptor (EGFR) mutations or gene fusions involving ALK, ROS1, and NTRK genes." (PMID 32224836, 2020). "Despite the high response rates (52.7%–83%) of TKIs used in treating patients with stage IIIb or IV lung cancer with active EGFR mutations, such patients eventually succumb to this disease; To further improve the outcome, more aggressive treatment might be necessary for some patients." (PMID 32702917, 2020). "Additionally, the potential of DGKη to regulate MAPK signaling, which is a downstream target of epidermal growth factor receptor (EGFR), led a group to study the oncogenic effects of DGKη in lung cancer, which is often characterized by mutations in EGFR and KRAS." (PMID 32722576, 2020). "Secondly, in some CT images of patients with lung cancer and atelectasis, enhanced images can more accurately delineate the edge of the lesion, reduce the impact on imaging features, and improve the diagnostic efficacy of the model for EGFR mutations in non-small cell lung cancer." (PMID 33117680, 2020). "The detection of EGFR mutations in ctDNA could guide treatment decision in lung cancers." (PMID 32093010, 2020).
lung cancer (continued). "Since lung cancers with a family history may indicate a potentially differed genetic background from sporadic cases, it is interesting to investigate if there is a relationship between family history of cancer and EGFR mutations in lung cancer patients, both of which participate in tumorigenesis." (PMID 31703574, 2019). "A recent clinical trial specifically excluding patients with EGFR‐mutations showed a longer overall survival (5.9 vs. 7.5 months for placebo treated vs. ruxolitinib treated, hazard ratio = 0.877) when combining ruxolitinib and chemotherapy in non‐small cell lung cancer patients (NCT02119650)." (PMID 31407334, 2019). "In addition, DBS also provides an alternative tool to formalin-fixed paraffin-embedded cell blocks for biobanking to detect epidermal growth factor receptor (EGFR) or Kirsten rat sarcoma 2 viral oncogene homolog (KRAS) mutation for personalized target therapy in lung cancer patients." (PMID 30777078, 2019). "Moreover, 52 paraffin-embedded tissues and matched fixation liquid of lung cancer biopsy with unknown EGFR mutation status were detected, and the EGFR mutation positive rate were 36.5% and 28.8% respectively." (PMID 31315782, 2019). "Third, lower smoking prevalence with lower tumor immunogenic landscape and higher EGFR mutation might lead to these results among women patients with lung cancer, and those female patients with EGFR tumor mutations receive no survival benefit from the immune checkpoint inhibitors." (PMID 31165589, 2019). "Hence, downregulation of DUOX1 in lung cancers could lead to altered EGFR internalization pathways, and could thereby promote nuclear EGFR targeting and associated tumorigenic functions." (PMID 30890751, 2019). "In addition, because we demonstrated that STAT3 induced HER3 expression in EGFR-positive lung cancers, the inhibition of STAT3 could prevent HER3-mediated EGFR-TKI resistance." (PMID 31619200, 2019). "Notably, COR induces cell cycle arrest at the G0/G1 phase in in vitro lung cancer cell line H1975 via decreasing the level of phosphorylated epidermal growth factor receptor (EGFR), subsequently causing a decrease in phosphorylated AKT and phosphorylated ERK1/2." (PMID 31207985, 2019). "Additionally, epidermal growth factor receptor (EGFR), which participates in signaling pathways associated with various tumors such as lung cancer, colorectal cancer, head and neck cancer, and breast cancer, and this gene has been previously noticed to be over expressed in glioblastoma." (PMID 31137733, 2019). "Therefore, pseudo-heterogeneous distribution of EGFR mutation is observed in lung cancer." (PMID 31014278, 2019). "In addition, Axl lead to EGFR-TKIs resistant by increasing expression and forming a hetero-dimerization with EGFR and inhibition of Axl could prevent or overcome acquired resistance to EGFR-TKIs in EGFR-mutated lung cancer." (PMID 31998131, 2019). "The oncogenic stress may explain the pathogenesis of EGFR mutation in lung cancer." (PMID 31703574, 2019). "Given that EGFR-mutated lung cancer was previously shown in a study based on NGS to have a lower mutation burden compared with lung cancer wild-type for EGFR, it may be difficult to identify concurrent actionable driver mutations in patients with EGFR or HER2 mutations." (PMID 29765525, 2018). "Treatment strategies of lung cancers have expanded greatly in recent years with the development of targeting therapy in cancer-specific oncogenic driver mutations, such as the epidermal growth factor receptor (EGFR), the anaplastic lymphoma kinase (ALK) and ROS1 rearrangements." (PMID 29515799, 2018). "There are 252 cancer-associated S768 mutations at EGFR (ProKinO), and two SNPs that result in the substitution of isoleucine for serine at position 768 (rs397517108 and rs121913465, neXtProt) are considered pathogenic or likely pathogenic in lung cancer, according to ClinVar20." (PMID 29695735, 2018).
lung cancer (continued). "Consequently, the combination of 3rd-gen EGFR TKIs and MEK inhibitors may be a reasonable strategy for the treatment of lung cancers with EGFR mutations and RAS activation." (PMID 29386539, 2018). "However systemic therapy for lung cancer has been revolutionized for the subsets of patients with an EGFR mutation, ALK rearrangement or PD-L1 positivity by targeted agents which are initiated in appropriate clinical scenarios and based on widely available predictive biomarkers." (PMID 30364202, 2018). "However, any mutation or polymorphism that affects EGFR expression or activity may theoretically modify lung cancer risk." (PMID 30011810, 2018). "However, persistent control of extra‐cranial site metastases has been described in many patients indicating that incomplete penetration of the brain–blood barrier by EGFR‐TKIs may be the main cause of CNS failure in lung cancer cases." (PMID 30350450, 2018). "However, aberrant expression of the EGFR via gene amplification, mutation, or protein overexpression results in dysregulation of EGFR-mediated signaling pathways with subsequent tumorigenesis, especially in lung cancer." (PMID 29548337, 2018). "However, considering that the CyclinD1-CDK4/6-Rb pathway is downstream of the EGFR signaling pathway, it is likely that this cell cycle pathway, which involves CDKN2B and RB1, plays an important role in lung cancer progression and/or therapeutic resistance in patients with EGFR active mutation." (PMID 29343775, 2018). "Likewise, TTF1, p63, NapsinA, K-ras, EGFR are associated with the oncogenesis of lung cancer." (PMID 28938549, 2017). "CT is a routinely used and relatively cost-effective modality in the diagnosis of lung cancer that presents various imaging features, some of which have been reported to relate with certain histopathological types, while these types have been identified to correlate with EGFR mutations." (PMID 28068946, 2017). "The participation of activating EGFR mutations in lung cancer cell mobility is unknown." (PMID 28881820, 2017). "Thus, we hypothesized that detecting the KRAS and EGFR mutation of cfDNA in liquid biopsies by CAST‐PCR may be applied to monitor the disease progression of lung cancer during therapy." (PMID 28382702, 2017). "Hence, to investigate the finding of clinical results and whether CBL could be a positive indicator for MET-targeted therapeutics in lung cancer, we used the EGFR L858R/T790M mutation cell line H1975." (PMID 28835699, 2017). "In conclusion, KRAS and EGFR mutations can be detected in peripheral blood as an alternative and supplement to tissue analysis; and quantitative levels of cfDNA, pmKRAS, and pmEGFR are associated to the clinical outcome of the surgical treatment of lung cancer." (PMID 28382702, 2017). "In addition to EGFR mutation-targeted therapy, multiple examples of genotype-directed therapy producing dramatic responses in molecular subtypes of lung cancer are emerging, including ALK rearrangements, ROS1 rearrangements, MET amplification, BRAF mutations, HER2 mutations, and RET rearrangements." (PMID 28099915, 2017). "Furthermore, a high or perfect concordance between primary tumour and metastasis has been seen in colorectal and lung cancer and between areas with different growth patterns within lung adenocarcinomas when looking at common driver mutations such as EGFR, KRAS, NRAS and BRAF." (PMID 28347348, 2017). "These could partially explain why mutant EGFR in lung cancer indicated higher risk of SREs." (PMID 29113396, 2017).
lung cancer (continued). "Furthermore, NF1-associated drug resistance to RAF and EGFR inhibitors, tamoxifen and retinoic acid, has been observed in melanoma, lung cancers, breast cancers and neuroblastoma, respectively, and melanoma cells with BRAF/NF1 mutations develop resistance to BRAF inhibitors." (PMID 28637487, 2017). "Furthermore, SHH-GLI1 signaling inhibition is involved in sensitization to EGFR-TKI (gefitinib/erlotinib)-based therapy, thereby reducing cellular viability, as well as the self-renewal function of cancer stem-like cells derived from the EGFR-mutated lung cancer cell lines H1650 and H1975." (PMID 28978016, 2017). "Therefore, the purpose of present study was to investigate whether PD 0332991 can reverse EGFR-TKI-resistance in human lung cancer cells in vitro and in vivo, and to explore the underlying mechanisms." (PMID 27825114, 2016). "Germline mutations of EGFR T790M and V843I were reported to confer an inherited susceptibility to lung adenocarcinoma, which may explain at least in part the phenomenon of family lung cancers." (PMID 27449093, 2016). "EGFR inhibitors have been previously reported to down-regulate PD-L1 expression in lung cancer cell lines carrying sensitizing EGFR mutations, suggesting that they may potentially function as immune-modulators in addition to their direct cytotoxic effects on tumor cells." (PMID 27467256, 2016). "Therefore, Mtb-mediated dysfunction of DNA repair might contribute to the progression of lung cancer due to long-term accumulation of mutations in DNA and the interspecies interaction between Rv1438 and EGFR." (PMID 27803888, 2016). "However, since EGFR mutations in lung cancers are commonly associated with gene amplification, p.T790M could be present in all tumor cells but only on one or a subset of the amplified EGFR TKI-sensitive mutant alleles." (PMID 27304188, 2016). "Thus, the therapeutic strategies for lung cancer patients with EGFR wild type, first mutation, or acquired mutation could be different." (PMID 27786281, 2016). "One-hundred and fifty two patients with activating EGFR mutations were included in this study and 136 patients' tumor sample were available for targeted sequencing of genomic alterations in 22 genes using the Colon and Lung Cancer panel (Ampliseq, Life Technologies)." (PMID 27121209, 2016). "Our findings indicate that the inactivation of NOTCH1 alone, without concomitant inhibition of EGFR, may lead to unexpected outcomes in lung cancer by increasing ERBB3 to promote EGFR-mutated tumour growth, providing a caution against indiscriminate use of NOTCH inhibitors." (PMID 27456471, 2016). "Thus, our study provides a rationale for conducting clinical studies to investigate combination therapy with EGFR inhibitors and PD1/PD-L1 axis blocking antibodies especially in EGFR-driven lung cancer with either as a result of sensitizing mutations or overexpression of wild type EGFR." (PMID 27467256, 2016). "Also, the observed association between DUOX1 expression and sensitivity to EGFR TKI may suggest that positive DUOX1 expression status in lung cancers may be suitable for therapeutic management with EGFR TKI, even if they express wild-type EGFR." (PMID 27694834, 2016). "In lung cancer and the molecular evaluation of EGFR mutation for therapeutic selection, inaccurate and overestimated tumor cell content could result in a false nagative test results, potentially leading to anti-EGFR therapy being withheld." (PMID 26317646, 2015). "Finally, the combination of LDCT and EGFR mutation detection using ctDNA may provide an attractive method for screening early-stage lung cancer which could be the best way to decrease the high mortality of lung cancer." (PMID 26448936, 2015). "Similarly, the resistance–conferring mutation EGFR T790M could be detected in plasma of lung cancer patients following treatment with gefitinib or erlotinib." (PMID 26524482, 2015).